SACK1E (scaffolding CK1 anchoring protein E)
Description:
May play a role in MAPK signaling.
Synonyms: FAM83E; FLJ20200
Tractability: No criterion of Open Targets' tractability assessment is met for any kind of drug.
Gene: Protein-coding gene on chromosome 19 (48,599,961 to 48,615,093, reverse strand). Ensembl gene ENSG00000105523.
Subcellular location: Cytoplasm; Cytoplasm, perinuclear region
Subcellular location (Human Protein Atlas): Cytosol; Vesicles
Gene Ontology:
Molecular function: protein binding; protein kinase binding
Biological process: signal transduction
Cellular component: cytoplasm; perinuclear region of cytoplasm
Genetic constraint (gnomAD): Loss-of-function variants: 30 observed, 28.59 expected, observed/expected ratio (o/e) 1.05, 90% interval 0.78 to 1.42. The synonymous counts are far from expectation, so gnomAD's model fits this gene poorly and the ratio says little. Missense variants: 686 observed, 591.79 expected, observed/expected ratio (o/e) 1.16, 90% interval 1.09 to 1.24. Synonymous variants: 309 observed, 253.51 expected, observed/expected ratio (o/e) 1.22, 90% interval 1.11 to 1.34.
Homologues: Orthologues: chimpanzee FAM83E (99% identical), macaque FAM83E (94% identical), dog FAM83E (81% identical), pig FAM83E (80% identical), guinea pig FAM83E (74% identical), rat Fam83e (73% identical), mouse Fam83e (72% identical), tropical clawed frog fam83e (41% identical), zebrafish fam83e (28% identical), zebrafish fam83fa (27% identical), zebrafish fam83fb (23% identical). Paralogues in human: SACK1G (33% identical), SACK1F (28% identical), SACK1D (28% identical), SACK1H (28% identical), SACK1B (27% identical), SACK1C (26% identical), SACK1A (23% identical).
Diseases named in the same sentence as SACK1E in open-access papers:
SACK1E is named in the same sentence as 8 diseases in open-access papers, as found by Europe PMC text mining. Sharing a sentence is not in itself a finding about the gene and the disease.
SACK1E shares sentences with these, for which no sentence is quoted: tumor (5 papers); cancer (4); lung carcinoma (2); ovarian carcinoma (2); bladder cancer (1); breast carcinoma (1); cognitive decline (1); posterior cortical atrophy (1).